MICD (MHC class I polypeptide-related sequence D (pseudogene))
Synonyms: PERB11.4
Gene: Unprocessed pseudogene on chromosome 6 (29,970,801 to 29,972,464, reverse strand). Ensembl gene ENSG00000229390.
Diseases named in the same sentence as MICD in open-access papers:
MICD is named in the same sentence as 5 diseases in open-access papers, as found by Europe PMC text mining. Sharing a sentence is not in itself a finding about the gene and the disease. The quoted sentences say what the papers report.
microcephaly (1 paper, 2025). A congenital or acquired developmental disorder in which the circumference of the head is smaller than normal for the person's age and sex. "Similar to mice lacking UBE3A, mICD mutants showed increased body weight and microcephaly compared to WT mice." (PMID 40877933, 2025).
multiple sclerosis (1 paper, 2018). A progressive autoimmune disorder affecting the central nervous system resulting in demyelination. "The SNPs rs2523946 and rs3823355 in the MICD gene loci are associated with multiple sclerosis susceptibility and are in LD with the SNP of rs4959039." (PMID 30083439, 2018).
nasopharyngeal carcinoma (1 paper, 2018). A carcinoma arising from the nasopharyngeal epithelium. "The SNP rs5009448 located in the MICD gene loci is among the frequent loss of heterozygosity loci at 6p in nasopharyngeal carcinoma in southern China specifically linked to Epstein Barr virus etiopathogenesis." (PMID 30083439, 2018).
MICD also shares sentences with these, for which no sentence is quoted: autoimmune disease (1 paper); skeletal disease (1).